PLK1 (polo like kinase 1)
Diseases named in the same sentence as PLK1 in open-access papers (continued):
Sharing a sentence is not in itself a finding about the gene and the disease.
non-small cell lung carcinoma (54 papers, 2004 to 2025). A group of at least three distinct histological types of lung cancer, including non-small cell squamous cell carcinoma, adenocarcinoma, and large cell carcinoma. "In non-small-cell lung carcinoma, the involvement of PLK1 in facilitating EMT and metastasis has been linked to the upregulation in the TGF-β/SMAD signaling pathway." (PMID 39451218, 2024). "The clinical study in non-small cell lung cancer patients showed that PLK1’s high expression was markedly associated with advanced clinical stage, higher tumor classification, and lymph node metastasis, and was an independent unfavorable prognostic biomarker for non-small cell lung cancer patients." (PMID 28724602, 2017). "However, Plk1 is highly overexpressed in non-small cell lung cancer, human head and neck cancer, and in patients with a poor prognosis, suggesting that overexpression of Plk1 promotes carcinogenesis and is closely associated with cancer aggression." (PMID 28430578, 2017). "In non-small cell lung cancer, the invasion and metastasis of tumor cells can be promoted by activating the PLK1/β-catenin/AP-1 or PLK1/TGF β axis." (PMID 40612941, 2025). "In TGF-β-induced EMT, PLK1 binds and phosphorylates Ser-311 of β-catenin to facilitate non-small cell lung cancer metastasis." (PMID 38351178, 2024). "Previously we found that catalytically active PLK1 drives EMT in non-small cell lung cancer (NSCLC), upregulating extracellular matrix factors including TSG6, laminin γ2, and CD44." (PMID 36793862, 2023). "An earlier review discussed Plk1, a critical regulator of mitosis, and its promising role in non-small cell lung cancer treatment." (PMID 36865478, 2023). "For example, hsa-miR-296-5p represses non-small cell lung cancer progression via directly targeting PLK1." (PMID 35590240, 2022). "It has been demonstrated that inhibition of PLK1 renders glioblastoma and non-small cell lung cancer cells sensitive to IR." (PMID 33898418, 2021). "When DNA double-strand breaks, ATM is a DNA damage signaling, and the reduction of ATM was found in CRC tumors, Plk1 was elevated in carcinomas of the non-small cell lung and other types of tumor, and it’s also play a crutial role in G2/M checkpoint recovery." (PMID 33925358, 2021). "PLK1 was shown to be overexpressed in a large spectrum of cancer types, including non-small cell lung cancer (NSCLC), breast ovarian and head and neck squamous carcinomas and melanoma." (PMID 29899826, 2018). "In non-small cell lung cancer, silenced PLK1 expression by iNOP-7-PLK1 siRNA reduced tumor growth in vitro and in vivo, and PLK1 was the target for miR-100 to regulate non-small cell lung cancer cell proliferation, apoptosis, and cell cycle." (PMID 28724602, 2017). "In non-small- cell lung cancer, PLK1 has been shown to be overexpressed in tumor tissues and cell lines." (PMID 28724602, 2017). "In this line of thinking, PLK1 inhibition has been reported to be effective in treating EGFR-inhibitor resistant non-small cell lung cancer through EMT." (PMID 28953239, 2017). "As an example, in early- to mid-stage non-small cell lung cancer, Claspin was only one of a set of five genes (POLQ, PLK1, RAD51, CDC6, and CLSPN) encoding proteins involved in the maintenance of genome stability that were found to be consistently upregulated and associated with poor survival." (PMID 41009395, 2025). "HIST1H2BH along with PLK1 might serve as a prognostic biomarker of non-small cell lung cancer patients." (PMID 36232772, 2022).
non-small cell lung carcinoma (continued). "Hence, under our five-gene risk score classification, the high-risk MPM patients may benefit from PLK1 specific small molecule inhibitors, which are currently considered to be attractive therapeutic strategies against specific tumor types such as leukemia and non-small cell lung cancer." (PMID 32849853, 2020). "In addition, the PLK1 inhibitor BI 2536 triggers mitotic catastrophe in non-small cell lung cancer cells through activation of the spindle assembly checkpoint." (PMID 28416758, 2017). "Its levels in non-small-cell lung cancer tumors correlate inversely with survival, indicating that PLK1 may have prognostic value." (PMID 22309939, 2012). "In non-small cell lung cancer, POLQ upregulates DNA replication initiation proteins such as CDC6 and PLK1, enhancing tumor cell tolerance to replication stress, promoting cell proliferation, and resulting in poor prognosis." (PMID 38270643, 2024). "Many studies have supported the involvement of PLK1 signaling in the EMT and metastasis of esophageal squamous cell, gastric, prostate, and non-small cell lung cancer (NSCLC)." (PMID 37968723, 2023). "To assess the relevance of PLK1 as a potential target for cancer therapy, we analyzed its expression in A549 and NCI-H460 non-small cell lung cancer (NSCLC) cell lines." (PMID 35745782, 2022). "BI 2536, a selective inhibitor of polo-like kinase 1 (PLK1), has been used in several clinical trials as a treatment for patients with AML (Clinicaltrials.gov: NCT00701766) and non-small-cell lung cancer (Clinicaltrials.gov: NCT02211833)." (PMID 35785164, 2022). "Here, we found that USP7 inhibition induces mitotic catastrophe and apoptosis effectively in paclitaxel-resistant non-small cell lung cancer (NSCLC), alone or in combination with the mitotic kinase PLK1 inhibitor volasertib." (PMID 33207738, 2020). "In addition, over-expression of POLQ, PLK1, RAD51, CDC6, and CLSPN was found to correlate with worse prognosis in non-small cell lung cancer." (PMID 41009395, 2025). "Furthermore, the combined inhibition of PLK1 and PI3K/AKT, along with FOXO1, exerts synergistic anticancer effects in anaplastic thyroid cancer and non-small cell lung cancer." (PMID 40612941, 2025). "For example, overexpression of PLK1, an early trigger for G2/M transition, is a negative prognostic factor in non-small-cell lung cancer patients." (PMID 33224985, 2020).
glioblastoma (50 papers, 2012 to 2025). The most malignant astrocytic tumor (WHO grade IV). "High expression of PLK1 inhibits the infiltration of M1 macrophages and their associated chemokines and marker genes into the glioblastoma immune microenvironment, whereas knockdown of PLK1 increases the infiltration and polarization of M1 macrophages." (PMID 40612941, 2025). "A single intracerebral injection of CRISPR–LNPs against PLK1 (sgPLK1–cLNPs) into aggressive orthotopic glioblastoma enabled up to ≈70% gene editing in vivo, which caused tumor cell apoptosis, inhibited tumor growth by 50%, and improved survival by 30%." (PMID 37166046, 2023). "For instance, the inhibition of PLK1 was reported to cause cell cycle arrest and lead to cell death in glioblastoma." (PMID 33176854, 2020). "To date, all work concerning the use of temozolomide (TMZ) in combination with a PLK1 inhibitor has been in the context of primary grade IV glioblastoma, which rarely carries an IDH1 mutation." (PMID 28178660, 2017). "Our results indicate that EGFRvIII expression is associated with increased PLK1 expression in glioblastoma cells." (PMID 26059434, 2015). "It has recently been reported that Plk1 inhibition may promote differentiation of glioblastoma stem cells triggered through loss of SOX2." (PMID 24204733, 2013). "For instance, LNPs encapsulating Cas9 mRNA and gRNAs targeting polo-like kinase 1 (PLK1) in a glioblastoma mouse model demonstrated effective gene editing and tumor suppression." (PMID 40292231, 2025). "We have also found that LCS1269 triggered G2 cell cycle block associated with Wee1/Myt1 axis activation, the upregulation of transcription factor Forkhead Box M1 (FOXM1), and its target Polo Like Kinase 1 (PLK1) in human glioblastoma cell lines." (PMID 40649791, 2025). "D‐Cb effectively delivers polo‐like kinase 1 (PLK‐1) antisense oligonucleotides (ASO) to treat glioblastoma in an orthotopic mouse model, demonstrating its potential as a carrier for brain‐targeted gene therapy." (PMID 39092676, 2025). "Being a proto-oncogene, PLK1 expression levels are significantly elevated in various malignancies, including glioblastoma, making it a potential therapeutic target for glioblastoma treatment." (PMID 37719847, 2023). "Inhibition of PLK1 combined with radiotherapy or temozolomide chemotherapy increased the efficiency of those treatments in glioblastoma models." (PMID 37228396, 2023). "With minimal (less than 0.5%) off‐target gene editing in high‐risk tissues, encapsulating nanocapsules demonstrated promising glioblastoma tissue targeting that resulted in up to 38.1% PLK1 gene editing efficiency in a brain tumor." (PMID 37166046, 2023). "To identify FOXM1 transcriptional activity in hypoxic glioblastoma cells, we focused on and investigated the protein expression of PLK1 and cyclin B1, two well-known downstream targets of FOXM1." (PMID 34740322, 2021). "In fact, it has been shown that JNJ induces mitotic arrest in glioblastoma-derived neuronal stem cells by inhibiting Plk1 phosphorylation." (PMID 30200644, 2018). "In this study, we evaluated the effects of PLK1 on glioblastoma and the synergistic inhibition effect of PLK1 inhibitor combined with TMZ on human brain glioma stem cells in vitro and vivo." (PMID 30133120, 2018). "We and others have demonstrated that PLK1 is a potential therapeutic target for brain tumors such as glioblastoma, medulloblastoma, and diffuse intrinsic pontine glioma (DIPG)." (PMID 29228610, 2017). "As such, our investigation on the selective killing of the glioblastoma cells that overexpress PLK1 by these molecules warrants further studies focused on brain tumors." (PMID 27557495, 2016). "Further, our results suggest that Ink4a/Arf(−/−) EGFRvIII glioblastomas that acquired resistance to EGFR inhibition retain oncogenic stress that requiring PLK1 compensation." (PMID 26059434, 2015).
glioblastoma (continued). "Our results indicate that glioblastomas harboring high levels of DNA damage accumulation, including those expressing EGFRvIII, are more likely to respond to PLK1 inhibitors." (PMID 26059434, 2015). "We found that PLK1 expression correlated with the DNA damage accumulation signature in TCGA dataset and another independent glioblastoma dataset, the Repository for Molecular Brain Neoplasia Data (REMBRANDT)." (PMID 26059434, 2015). "A comparison using The Cancer Genome Atlas (TCGA) glioblastoma database revealed that EGFRvIII+ glioblastomas exhibited higher cyclin-normalized PLK1 expression than the EGFRvIII- glioblastomas (p = 0.01)." (PMID 26059434, 2015). "Taken together, these results suggest that PLK1 counteracts excessive DNA damage accumulation by promoting HR in EGFRvIII expressing glioblastoma cells." (PMID 26059434, 2015). "With the emergence of selective inhibitors of PLK1, there has been growing interest in their clinical application to glioblastomas." (PMID 26059434, 2015). "The synthetic lethal interaction suggests that EGFRvIII expressing glioblastomas harbored heightened requirement of PLK1 activity." (PMID 26059434, 2015). "In addition, PLK1 was up-regulated by CoCl2 treatment, which generated PGCCs, and PLK1 blockage sensitized glioblastoma cells to ionizing radiation." (PMID 38129519, 2023). "Furthermore, a novel LNPs CRISPR-Cas9 formulation (sgPLK1-cLNPs) had permitted a safe and effective (~70%) gene editing in vivo of aggressive orthotropic glioblastoma cells by targeting their PLK1 (polo-like kinase 1) gene." (PMID 37545694, 2023). "Immune infiltration analysis demonstrated that highly expressed PLK1 inhibited M1 macrophages infiltration to glioblastoma immune microenvironment by Quantiseq and Xcell databases and negatively related to some chemokines and marker genes of M1 macrophages in glioblastoma." (PMID 36618405, 2022). "Additionally, a series of experiments showed the synergistic inhibition effect of PLK1 inhibitor with TMZ on glioblastoma stem‐like cells growth in vitro and vivo." (PMID 30133120, 2018). "We determined whether glioblastoma cells with acquired resistance to EGFR inhibitors maintain cell states with oncogenic stress that require PLK1 as a compensatory mechanism." (PMID 26059434, 2015). "In the context of our previous finding that EGFRvIII expression is associated with an elevated level of DNA damage, we hypothesized that PLK1 prevented the lethal accumulation of DNA damage in EGFRvIII expressing glioblastomas." (PMID 26059434, 2015). "Given that PLK1 inhibition resulted in an increased level of DNA damage in EGFRvIII expressing glioblastoma cells, we next tested whether the PLK1-mediated Rad51 phosphorylation played a significant role in glioblastomas." (PMID 26059434, 2015). "Sox2 expression was regulated by PLK1 in glioblastoma multiform cells and PLK1 inhibition could delay tumor progression in mice." (PMID 23554769, 2012). "ESTIMATE analysis showed that the expression of PLK1 negatively correlated with the infiltration of immune cells and stromal cells in glioblastoma multiforme (GBM)." (PMID 36618405, 2022). "In addition, PLK1 can suppress the apoptosis of glioblastoma cells." (PMID 34115550, 2021). "Among these common repurposed drugs, BI-2536 is a PLK1 inhibitor and it has been reported that PLK1 level is elevated in glioblastoma multiforme (GBM) and its inhibition restricts the growth of brain cancer cells." (PMID 29020948, 2017). "As many studies had documented the important roles of PLK1 in cell proliferation in both normal cell and transformed cell, it had been demonstrated that the inhibition of PLK1 in glioblastoma could result in decreased proliferation by arresting cell cycle and leading to cell death." (PMID 26090465, 2015).
glioblastoma (continued). "Analysis of essential regulators of the G2/M and spindle assembly checkpoints (PLK1, TTK/MPS1), mitotic spindle dynamics (KIF11) and sister chromatid separation (PTTG1/securin) confirmed their down-regulation in a panel of glioblastoma cell lines." (PMID 33478100, 2021). "As a result of the downregulation of PLK1 by DSF, the growth of the primary glioblastoma cell lines BT74 and GBM4 was diminished." (PMID 33260923, 2020). "Inhibition of PLK1 kinase activity by PLK1 inhibitors such as volasertib, BI 2536, and GSK461364 has been shown to induce cell cycle arrest at the G2/M phase in glioblastoma cells, osteosarcoma and NSCLC cells." (PMID 29983892, 2018). "In agreement with that, PLK1 and EGFR inhibitor have been described as orthogonal therapeutic agents in glioblastoma, with enhanced tumoricidal activity when combined." (PMID 29844324, 2018). "In summary, our study demonstrated pre-clinical efficacy of combining TMZ, PLK1 and EGFR inhibitors as treatment for EGFRvIII expressing glioblastomas." (PMID 26059434, 2015). "The tumoricidal and TMZ-sensitizing effects of the PLK1 inhibitor, BI2536, depends on the intrinsic physiology of the glioblastoma and correlated with the endogenous levels of DNA damage." (PMID 26059434, 2015). "Polo-like kinase 1 (PLK1), highly expressed in various primary tumor tissues including glioblastomas, thyroid cancer, head and neck squamous cell carcinoma, and acute myeloid leukemia, has become a promising target for cancer therapy due to its role in promoting tumorigenesis." (PMID 39763588, 2024). "Since inhibition of DDR and induction of DNA damage often result in synergistic tumor ablation, our results suggest that PLK1 inhibition would enhance the tumoricidal effect of TMZ, the DNA damaging chemotherapeutic agent routinely used in glioblastoma treatment." (PMID 26059434, 2015). "The tumoricidal and TMZ-sensitizing effects of BI2536 were uniformly observed across Ink4a/Arf(−/−) EGFRvIII glioblastoma clones that acquired independent resistance mechanisms to EGFR inhibitors, suggesting these resistant clones retain oncogenic stress that required PLK1 compensation." (PMID 26059434, 2015). "Moreover, it has recently been described that MELK interacts with the transcription factor FOXM1 (a master regulator for cell proliferation) in a Plk-1-dependent manner and that EZH2-mediated radiation resistance occurs through a MELK-FOXM1-dependent manner in glioblastoma cells." (PMID 31740676, 2019). "Moreover, we have previously identified LCS1269 as a potential anti-glioblastoma agent, probably interfering with cell cycle regulation through both direct CDK1 inhibition and indirect modulation of CDK1 activity through Wee1/Myt1 and FOXM1/Plk1 signaling pathways." (PMID 40649791, 2025).